CTSB (cathepsin B)
Diseases named in the same sentence as CTSB in open-access papers (continued):
Sharing a sentence is not in itself a finding about the gene and the disease.
fascioliasis (4 papers, 2008 to 2023). A parasitic infection that is caused by liver flukes, usually Fasciola hepatica, of sheep, goats, and cattle. "A significant decrease in lysosomal as well as in the total activity of cathepsin B during fasciolosis was also observed." (PMID 19696938, 2008). "Cathepsin B is potential target for vaccine and antihelminthics drugs for control of fascioliasis." (PMID 32595713, 2020). "According to the importance of pH and temperature in the life cycle of F. hepatica, determination of the optimum pH and temperature activity for cathepsin B in the miracidia and eggs of this parasite may help us for prevention and controlling of fascioliasis." (PMID 32595713, 2020). "A significant decrease in lysosomal as well as in the total activity of cathepsin B during fasciolosis was also observed (by about 18%, 23%, and 15% for lysosomal and by about 40%, 42%, and 25% for total in comparison with control group in the 4th, 7th, and 10th wpi, respectively)." (PMID 19696938, 2008).
glaucoma (4 papers, 2012 to 2022). Increased pressure in the eyeball due to obstruction of the outflow of aqueous humor. "Given the relevance of TGFβ and EMT in glaucoma pathogenesis, we investigated a potential regulatory effect of CTSB in these biological processes in TM cells." (PMID 33379277, 2020). "Recently, it has been shown that CTSB expression is inhibited in the TM of glaucoma patients." (PMID 35806375, 2022). "Besides, the levels of cathepsin B and D were significantly raised in cells displayed glaucoma like symptoms." (PMID 32666339, 2020). "Similar approaches targeted at enhancing CTSB activity or restoring CTSB levels in the glaucomatous TM could be developed to attenuate fibrosis and ECM deposition in the TM in glaucoma." (PMID 33379277, 2020).
head and neck cancer (4 papers, 2014 to 2024). A primary or metastatic malignant neoplasm affecting the head and neck. "The results of our study demonstrate the important role of EMMPRIN-2 in head and neck cancer progression for the first time and reveal that increased extracellular secretion of Cathepsin B may be a novel mechanism underlying EMMPRIN-2 enhanced tumor progression in head and neck cancer." (PMID 24705283, 2014). "Mechanistic studies revealed that EMMPRIN-2 overexpression promoted the secretion of extracellular signaling molecules, including matrix metalloproteinases-2(MMP-2), urokinase-type plasminogen activator(uPA) and Cathepsin B, in head and neck cancer cells." (PMID 24705283, 2014). "Interestingly, profound CTSB upregulation was also found in head and neck cancer tissues compared with paired adjacent normal tissues." (PMID 32106632, 2020). "More importantly, we observed that the siRNA-mediated down-regulation of Cathepsin B significantly attenuated the EMMPRIN-2-induced migration, adhesion and invasion of head and neck cancer cells." (PMID 24705283, 2014). "Our current study provided strong evidence indicating that Cathepsin B functions as an important mediator of EMMPRIN-2 induced signaling, thereby promoting cell migration and invasion in head and neck cancer." (PMID 24705283, 2014). "An interesting finding from this study was the identification of Cathepsin B as a downstream mediator of EMMPRIN-2 signaling during the migration and invasion of head and neck cancer cells." (PMID 24705283, 2014). "We found that EMMPRIN-2 overexpression and Cathepsin B down-regulation significantly inhibited the invasion, migration and adhesion of Tca8133 cells, suggesting that Cathepsin B is required for EMMPRIN-2 enhanced cell migration and invasion in head and neck cancer." (PMID 24705283, 2014). "To identify the underlying mechanisms governing the effects of EMMPRIN-2 on cancer cell invasion and metastasis, we examined the expression and secretion of uPA, Cathepsin B and MMP-2 in head and neck cancer cells after exogenously modulating the expression of EMMPRIN-2." (PMID 24705283, 2014). "Although participation of Cathepsin B in tumor initiation and progression has been suggested in several human malignancies, its fundamental importance in head and neck cancer has not been reported." (PMID 24705283, 2014).
Hyperglycemia (4 papers, 2020 to 2025). An increased concentration of glucose in the blood. "Although Cathepsin B/D have been implicated in hyperglycemia-anti-autophagic and pro-apoptotic effects under PDR, Cathepsin H’s specific role in retinal vascular pathology remains uncharacterized." (PMID 40616157, 2025). "It has been found that DAMP signals that can be sensed by the NLRP3 inflammasome include hypokalemia, hypercalcemia, hyperglycemia, cathepsin B, adenosine triphosphate (ATP), and reactive oxygen species (ROS), etc.." (PMID 34381452, 2021). "Hypokalemia, hypercalcemia, cathepsin B, Silica, Aβ, ATP, hyperglycemia, ROS, etc." (PMID 34381452, 2021). "Furthermore, in high glucose (HG)-treated retinal vascular endothelial cell cultures recapitulating the cathepsin expression patterns, Cathepsin B or D downregulation mediated the HG-induced anti-autophagic and pro-apoptotic effects, thereby may contribute to vascular lesions under hyperglycemia." (PMID 33293479, 2020).
invasive carcinoma (4 papers, 2014 to 2024). A carcinoma that is not confined to the epithelium, and has spread to the surrounding stroma. "Cathepsin B expression was significantly higher in invasive carcinomas NST compared with invasive lobular carcinomas (high in 30.5% vs. 8.6%, p < 0.05)." (PMID 39331316, 2024). "ELISA and qPCR was used to measure cathepsin B expression in HeLa cells and 169 tissue samples from invasive carcinomas, precancerous and normal tissues (p < 0.01)." (PMID 28250389, 2014). "A role for cathepsin B is further supported by studies showing that suppression of cystatin A, an endogenous inhibitor of cathepsin B, increases progression of DCIS to invasive carcinoma." (PMID 28506312, 2017).
lung squamous cell carcinoma (4 papers, 2013 to 2023). "As for the respiratory tract, lung squamous cell carcinoma (LUSC) showed a significantly higher expression level of CTSB than the normal lung tissues." (PMID 35155389, 2022).
lymphoma (4 papers, 2015 to 2019). A malignant (clonal) proliferation of B- lymphocytes or T- lymphocytes which involves the lymph nodes, bone marrow and/or extranodal sites. "It is certain that combining cathepsin-B with a simple clinical variable such as age did greatly enhance lymphoma-TB separation." (PMID 26962828, 2016). "First, it is the ‘warhead' of brentuximab vedotin, a clinically used ADC for CD30 lymphomas that is attached through a cathepsin B sensitive and self-immolative linker." (PMID 27698471, 2016). "The pathophysiological implication of this lysosomal ceramide/CTSB/XIAP axis in apoptotic cell death should be clarified in the future to develop a targeting therapy for NK/T lymphoma." (PMID 25855965, 2015). "The ASM–ceramide–CTSB signaling axis is a novel pathway of ceramide-mediated apoptosis in IL-2-deprived NK/T lymphoma cells." (PMID 25855965, 2015). "Finally, in the third, cathepsin-B was able to discriminate 12 lymphomas with high ADA levels from 12 TB with 100% sensitivity (95% CI 73.5–100%) and 83.3% specificity (95% CI 51.6–98%)." (PMID 26962828, 2016). "To investigate the validity of these assessments, we further compared the cathepsin B and S cleavage prediction data with those reported from IGHV-derived peptides eluted from HLA class II on lymphoma cells from two patients with mantle cell lymphoma." (PMID 31569504, 2019). "In summary, our present work demonstrated a novel pathway related to lysosomal ceramide, CTSB, and XIAP in IL-2(−)-induced NK/T lymphoma cell apoptosis." (PMID 25855965, 2015). "However, how ASM-generated lysosomal ceramide is related to the cathepsin family, including CTSB and CTSD and XIAP in NK/T lymphoma cell apoptosis, is poorly understood." (PMID 25855965, 2015). "Finally, we investigated whether exogenous C2-ceramide mimics IL-2(−)-mediated CTSB activation, XIAP degradation, and caspase-dependent NK/T lymphoma cell apoptosis." (PMID 25855965, 2015). "Finally, a pleural fluid cathepsin-B level <0.31 ng/mL yielded 89% sensitivity (95% CI 65.3–98.6%), 62% specificity (95% CI 43.6–77.8%), LR positive of 2.3 (95% CI 1.5–3.7), and LR negative of 0.18 (95% CI 0.05–0.68) for separating 18 lymphomas from 34 TB." (PMID 26962828, 2016).
malignant glioma (4 papers, 2011 to 2025). A grade III or grade IV glioma arising from the central nervous system. "We also demonstrated that CTSB is highly-expressed in known malignant glioma molecular phenotypes such as IDH wild-type, MGMT promoter unmethylation, 1p19q non-codeletion and mesenchymal subtype." (PMID 35277559, 2022). "Combinational therapeutic approaches targeting both cathepsin B and uPAR have been shown by Rao and colleagues to inhibit tumor progression and neovascularization in malignant glioma." (PMID 22093547, 2011). "The results above suggested that CTSB may be a potential biomarker of malignant gliomas." (PMID 35277559, 2022).
metabolic syndrome (4 papers, 2013 to 2025). A cluster of metabolic risk factors for CARDIOVASCULAR DISEASES and TYPE 2 DIABETES MELLITUS. "Interestingly, the expression of some of these genes (C1S, SAA2, ALCAM, CTSB, YKL-40 and tenomodulin) was found to be associated with some relevant metabolic syndrome features." (PMID 23975165, 2013). "Third, while this study highlights the CTSB–glycolysis–urate handling axis, its relevance in other pathological settings such as CKD, gout, or metabolic syndrome remains to be validated." (PMID 40457023, 2025).
nasopharyngeal carcinoma (4 papers, 2016 to 2025). A carcinoma arising from the nasopharyngeal epithelium. "High expression of CTSD and CTSB was detected in biopsy tissues from nasopharyngeal carcinoma (NPC)." (PMID 26995190, 2016). "In patients with nasopharyngeal carcinoma, a previous study found that serum CTSB levels are closely associated with tumor stage and lymph node metastasis, consistent with its role in extracellular matrix remodeling and tumor invasion." (PMID 41309848, 2025).
pancreatic adenocarcinoma (4 papers, 2020 to 2023). "High cathepsin B expression in lung, ovarian, pancreatic neuroendocrine cancers and pancreatic adenocarcinomas, is negatively correlated with survival and positively associated with recurrence, invasion, and/or tumor grade." (PMID 38026637, 2023). "Results showed the upregulation of CTSL/B and ACE2 in Pancreatic adenocarcinoma (PAAD) and Stomach adenocarcinoma (STAD) and demonstrated a positive correlation between copy number alteration (CNA) and gene expression for CTSB in PAAD and STAD." (PMID 33231569, 2020).
pancreatic neuroendocrine cancer (4 papers, 2015 to 2023). "Interestingly, CtsB, H, and S secreted by macrophages in pancreatic neuroendocrine cancer reduced progression by increased apoptosis and reduced angiogenesis." (PMID 31340550, 2019).
renal cell carcinoma (4 papers, 2019 to 2025). "In the case of renal cancer, the upregulation of CtsB was shown to decrease three- and five-year patient survival rates, and CtsK was shown to be overexpressed in renal cell carcinoma patients with Xp11 translocation." (PMID 32455715, 2020).
reovirus infection (4 papers, 2005 to 2026). "It remains to be established how the cathepsin B downregulation facilitates the persistent reovirus infection." (PMID 26712782, 2015). "The increased sensitivity to reovirus infection of the cells in spheroid cultures may be related to the high levels of active cathepsin B within the spheroids." (PMID 26712782, 2015). "Following reovirus infection, IFN-β mRNA levels significantly decreased, by more than 75% in the presence of either cathepsin B inhibitor or cathepsin L inhibitor in the tumor cells, regardless of susceptibility to reovirus." (PMID 25866783, 2015).
SARS-CoV infection (4 papers, 2020 to 2022). "The results indicate that SARS-CoV infection enhances the expression level of CTSB and TMPRSS2 genes after 1 day and 2.5 days, respectively." (PMID 34407143, 2021). "Whereas CTSB showed upregulation in SARS-CoV infection after 24 hr (GSE47962) in human airway epithelial cells." (PMID 34407143, 2021). "Yet, successful SARS-CoV infection of TMPRSS2 knockout mice was observed, demonstrating the ability of SARS-CoV and suggesting the ability of SARS-CoV-2 to use Cathepsin B/L in vivo." (PMID 33290397, 2020). "SARS-CoV infection was blocked by specific inhibitors of the pH-sensitive endosomal protease cathepsin L. S-mediated entry into Vero E6 and 293T/hACE2 cells was blocked by leupeptin, Z-lll-FMK (an inhibitor of both CTSB and CTSL), and E64c (an inhibitor of cysteine proteases)." (PMID 34239932, 2021).
worm infection (4 papers, 2011 to 2015). "The purpose of this study was to identify a cathepsin B of Clonorchis sinensis (CsCB) and to investigate its diagnostic value for human helminthiases." (PMID 21794140, 2011). "To find out whether CB could be applied for serodiagnosis in C. sinensis infection, we identified a gene encoding cathepsin B of C. sinensis (CsCB) and investigated its diagnostic value for human helminthiases." (PMID 21794140, 2011). "Here we demonstrate that sub-cutaneous injection of functionally active S. mansoni cathepsin B1 (SmCB1), or a cathepsin L from a related parasite Fasciola hepatica (FhCL1), elicits highly significant (P<0.0001) protection (up to 73%) against an experimental challenge worm infection." (PMID 24465551, 2014).
acute kidney injury (3 papers, 2022 to 2025). Sudden and sustained deterioration of the kidney function characterized by decreased glomerular filtration rate, increased serum creatinine or oliguria. "CTSB has been shown to be significantly involved in the pathogenesis of various kidney diseases, such as acute kidney injury (S-AKI and metal-induced AKI), diabetic nephropathy, polycystic kidney disease, hyperuricemia nephropathy, kidney cancer, glomerulonephritis, and kidney transplantation." (PMID 40129990, 2025).
adenovirus infection (3 papers, 2015 to 2023). "Rupture of the release of late endosomes and cathepsin B into the cytosol following adenovirus infection has been shown to activate the NALP3 inflammasome." (PMID 25866783, 2015). "In adenovirus infection, cathepsin B release is also required, although the inhibition of ROS attenuates IL-1β secretion, which suggests that cathepsin B may induce inflammasome activation through the promotion of ROS." (PMID 31284572, 2019). "In an adenovirus infection, cathepsin B release is also a mediator of inflammation, but reactive oxygen species (ROS) inhibition reduces IL-1β secretion, indicating that ROS production might be the mechanism of the induction of inflammasome activation by cathepsin B." (PMID 37189787, 2023).
cardiomyopathy (3 papers, 2021 to 2024). A disease of the heart muscle or myocardium proper. "Cathepsin-B is also known to mediate cardiac remodeling events and play a role in the progression of cardiomyopathy phenotype through cell death pathways." (PMID 37760023, 2023).
chronic kidney disease (3 papers, 2023 to 2025). Impairment of the renal function secondary to chronic kidney damage persisting for three or more months. "For example, in hypoxia-induced chronic kidney disease, results from network pharmacology and molecular docking research suggest that CTSB and IL-1β may be key targets for treating hypoxic kidney injury." (PMID 40129990, 2025). "In addition, green tea polyphenols play a similar role in high-fat diet-induced chronic kidney disease, where green tea polyphenols improve autophagy flux by affecting CTSB, which ultimately exerts a protective effect on the kidneys." (PMID 40129990, 2025). "Cathepsin B is involved in inflammation, apoptosis and autophagy during ESKD, chronic kidney disease, and AKI47." (PMID 37188670, 2023).
Crohn disease (3 papers, 2022 to 2024). A gastrointestinal disorder characterized by chronic inflammation involving all layers of the intestinal wall, noncaseating granulomas affecting the intestinal wall and regional lymph nodes, and transmural fibrosis. "Reverse Mendelian randomization analyses suggested that ulcerative colitis (UC) might lead to elevated cathepsin G levels, while Crohn’s disease (CD) may cause a decrease in cathepsin B and L1 levels." (PMID 39359476, 2024). "The sensor exhibited an accurate and sensitive cathepsin B detection with a good recovery (86–102%) and %RSD (< 11%) and could distinguish between the different stages of Crohn’s disease." (PMID 36944950, 2023).
cystic fibrosis (3 papers, 2021 to 2024). Autosomal recessive disorder caused by pathogenic variants in the CFTR gene (cystic fibrosis transmembrane conductance regulator), which encodes a chloride and bicarbonate channel expressed in epithelial cells, and follow the diagnosis criteria. "Cystic fibrosis is another disease that shows the combination of ENaC functioning and cathepsin B. In both normal and cystic fibrosis human bronchial epithelial cultures, cathepsin B was found in the apical plasma membrane and the airway surface liquid (ASL)." (PMID 38139392, 2023). "CTSB, CTSL, and CTSS are overexpressed in lung tissues of patients with cystic fibrosis." (PMID 39559762, 2024).
diabetic cardiomyopathy (3 papers, 2023 to 2025). Diabetic cardiomyopathy is a disorder of the heart muscle in people with diabetes. "CTSA and cathepsin B (CTSB) are capable of worsening diabetic cardiomyopathy and exacerbating cardiac impairment." (PMID 39964999, 2025). "Cathepsin B exacerbates diabetic cardiomyopathy by promoting NLRP3-mediated pyroptosis." (PMID 37766966, 2023).
endothelial dysfunction (3 papers, 2017 to 2020). In vascular diseases, endothelial dysfunction is a systemic pathological state of the endothelium (the inner lining of blood vessels) and can be broadly defined as an imbalance between vasodilating and vasoconstricting substances produced by (or acting on) the endothelium. "Taken together, this study demonstrates that CFTR upregulation protects against PA-induced endothelial dysfunction through improving autophagic flux with an underlying mechanism being involved in enhancing Atg12-Atg5-Atg16L complex formation and restoring the CTSB and CTSD protein expression." (PMID 33123317, 2020).
esophageal adenocarcinoma (3 papers, 2015 to 2021). A malignant tumor with glandular differentiation arising predominantly from Barrett mucosa in the lower third of the esophagus. "Noteworthy, AXL has been shown recently to mediate the anterograde trafficking of lysosomes (Lamp1-positive vesicles) in esophageal adenocarcinoma cells, regulating the secretion of cathepsin B, which is involved in matrix degradation and invasion." (PMID 31963783, 2020). "We employed the nanoneedle sensor to map CTSB activity within excised tissue samples from esophageal adenocarcinoma patients." (PMID 26197973, 2015). "The same sensor applied to tissue can map Cathepsin B activity with high resolution across the tumor margin area of esophageal adenocarcinoma." (PMID 26197973, 2015).
giardiasis (3 papers, 2017 to 2022). An infection of the small intestine caused by the flagellated protozoan giardia lamblia. "Proteomic profiling of Giardia trophozoites demonstrated that cysteine proteases, especially cathepsin L (catL)-like and cathepsin B (catB)-like enzymes, may be associated with the increased pathophysiological responses during giardiasis." (PMID 34022771, 2022).
gouty arthritis (3 papers, 2023 to 2025). "Proteomic analysis showed that the expressions of proteases Cathepsin B, Cathepsin D, Cathepsin G, and Cathepsin S in synovial fluid patients with gouty arthritis were significantly increased." (PMID 37069596, 2023). "Cathepsin B and cystatin C play a pro-inflammatory role in gouty arthritis of the knee joint." (PMID 40584622, 2025).